HTT (huntingtin)
Diseases named in the same sentence as HTT in open-access papers (continued):
Sharing a sentence is not in itself a finding about the gene and the disease.
Huntington disease (continued). "Huntington disease (HD) is a fatal, inherited neurodegenerative disorder caused by a mutation in the huntingtin (HTT) gene." (PMID 33192449, 2020). "HIP1 has been shown to be a direct interactor of huntingtin (the causal protein mutated in Huntington’s disease)." (PMID 31535203, 2020). "Huntington’s disease is characterized by a pathologic mutation consisting of an expanded CAG repeat in the huntingtin gene (HTT) on chromosome 4, encoding the huntingtin (htt) protein." (PMID 33015059, 2020). "Huntington’s disease (HD) is a hereditary neurodegenerative disease caused by a polyglutamine expansion in the huntingtin protein, Striatum atrophy in HD leads to a progressive disturbance of psychiatric, motor, and cognitive function." (PMID 32317916, 2020). "Huntington’s disease (HD) is an inherited disorder caused by the polyglutamine (poly-Q) mutations of the HTT gene results in neurodegeneration characterized by chorea, loss of coordination, cognitive decline." (PMID 33228685, 2020). "Here, we show that mutant huntingtin (mHtt) aggregates associated with Huntington disease transfer anterogradely from presynaptic to postsynaptic neurons in the adult Drosophila olfactory system." (PMID 32463364, 2020). "The pathogenesis of Huntington’s disease (HD), an inherited progressive neurodegenerative disease, is highly associated with the cytotoxicity-inducing mutant huntingtin (mHtt) protein." (PMID 32158393, 2020). "These include amyloid-β or tau in Alzheimer’s disease, α-synuclein in Parkinson disease or aberrant polyglutamine stretches in mutated huntingtin in Huntington’s disease." (PMID 32906744, 2020). "Huntington’s disease (HD) is a severe neurodegenerative disorder caused by a CAG triplet expansion in the first exon of the HTT gene." (PMID 33182269, 2020). "Huntington's disease is caused by a CAG-repeat expansion in exon 1 of the huntingtin gene, which leads to a long polyglutamine (polyQ; n = 35–60+) stretch on the N-terminal end of the Huntingtin protein (Htt)." (PMID 33101165, 2020). "Huntington’s disease is a progressive neurodegenerative disorder caused by the expansion of a polyglutamine stretch within the Huntingtin gene." (PMID 32566927, 2020). "A pathological association between an autosomal dominant neurological disorder caused by brain accumulation in mutated huntingtin (mHTT), known as Huntington disease (HD), and DM, has been reported." (PMID 32547392, 2020). "Although mutations in the huntingtin gene due to poly‐Q expansion cause Huntington's disease (HD) in humans, the normal function of HTT remains obscure." (PMID 31774219, 2020). "This indicates that wild-type HTT is relevant for neuronal development, which was recently proven by a study analyzing tissue from human fetuses that carry the Huntington’s disease mutation." (PMID 34968288, 2020). "Huntington disease (HD) is a fatal neurodegenerative disorder that is caused by CAG expansion mutation of the Huntingtin gene (HTT), which codes for polyglutamine." (PMID 32581130, 2020). "The protein aggregates observed in Huntington's Disease are caused by a polyglutamine expansion in the N-terminus of the huntingtin protein (Htt)." (PMID 32596207, 2020). "Huntington's disease (HD) is monogenic neurodegenerative disorder caused by CAG expansions within the Huntingtin gene (Htt); it has a prevalence of 1 in 10,000 worldwide and is invariably fatal." (PMID 32219094, 2020). "Huntington's disease (HD) is a devastating neurodegenerative disease caused by polyglutamine (polyQ) expansion in the huntingtin (HTT) gene." (PMID 32865873, 2020). "Huntington disease (HD) is caused by an expansion mutation of the N-terminal polyglutamine of huntingtin (mHTT)." (PMID 32581130, 2020). "Trinucleotide (CAG) repeat expansions longer than 39 in the huntingtin (HTT) gene cause Huntington’s disease (HD)." (PMID 32555394, 2020).
Huntington disease (continued). "Huntington’s disease (HD) mutation consists of a CAG expansion beyond the normal 10–35 repeats of the IT15 gene localized on the short arm of chromosome 6, encoding the huntingtin protein." (PMID 33066292, 2020). "Huntington’s disease (HD) is caused by trinucleotide CAG repeat expansions in the first exon of the huntingtin (HTT) gene." (PMID 33292395, 2020). "Huntington’s disease (HD) is caused by the expression of a mutated variant of Huntingtin (mHtt), which results in the complex pathology characterized by a defective function of the nervous system and altered inflammatory responses." (PMID 32220257, 2020). "The molecular mechanisms that link huntingtin mutation to neuronal cell death in Huntington’s disease (HD) are still not fully understood." (PMID 32448329, 2020). "Huntington's disease (HD) is a progressive neurodegenerative disorder caused by an expansion of the CAG trinucleotide repeat region in the huntingtin (HTT) gene on chromosome 4." (PMID 33370315, 2020). "Huntington’s disease (HD) is an autosomal dominant neurodegenerative disease produced by a mutation of the gene huntingtin (HTT, Albin and Tagle, 1995)." (PMID 33362481, 2020). "A CAG repeat expansion in the HTT gene that encodes the Huntingtin protein causes Huntington’s disease (HD)." (PMID 33324928, 2020). "Huntington disease (HD) is a devastating neurodegenerative disorder caused by a CAG repeat expansion in the huntingtin gene." (PMID 33250715, 2020). "Huntington disease (HD) is an autosomal dominant neurodegenerative disease caused by an expanded polyglutamine encoding CAG tract in the huntingtin (HTT) gene." (PMID 33192449, 2020). "Huntington disease (HD) is a hereditary neurodegenerative disorder caused by mutant huntingtin (mHTT)." (PMID 32978366, 2020). "Huntington’s disease (HD) is a fatal neurodegenerative disease caused by a CAG expansion mutation in the huntingtin gene." (PMID 31979301, 2020). "Huntington’s disease (HD) is an autosomal dominant neurodegenerative disease triggered by an expanded cytosine–adenine–guanine (CAG) triplet in the gene encoding the Huntingtin (HTT) protein, which initially affects the striatum and cortex." (PMID 32784556, 2020). "Huntington's disease (HD) is an autosomal dominantly inherited neurodegenerative disorder caused by a trinucleotide repeat expansion in the Huntingtin gene." (PMID 33329316, 2020). "Formation of intracellular mutant Huntingtin (mHtt) aggregates is a hallmark of Huntington’s disease (HD)." (PMID 32849783, 2020). "Huntington’s disease (HD) is an incurable neurodegenerative disorder caused by CAG trinucleotide expansions in the huntingtin gene." (PMID 32448329, 2020). "Huntington's disease (HD) develops in individuals with extended cytosine‐adenine‐guanine (CAG) repeats within the huntingtin (HTT) gene, causing neurodegeneration and progressive motor and cognitive symptoms." (PMID 32686867, 2020). "Huntington’s disease (HD) is a dominant hereditary disease caused by a mutation in IT15 gene that encodes huntingtin protein (Htt)." (PMID 32848594, 2020). "Huntington's disease (HD) is an autosomal dominant neurodegenerative disorder caused by an expanded polyglutamine (polyQ) tract in exon 1 of the huntingtin gene on the short arm of chromosome 4." (PMID 32865873, 2020). "In Huntington disease (HD), an extension of polyQ (polyglutamine) tract in the N-terminus of Huntingtin (HTT) protein causes protein aggregation." (PMID 32120776, 2020). "Huntington’s disease (HD) is a genetic neurodegenerative disease caused by expanded CAG triplet repeats in the first exon of HTT gene." (PMID 32849783, 2020). "Huntington’s disease (HD) is a hereditary autosomal dominant neurodegenerative disease caused by an unstable expansion of over 35 glutamines in the amino-terminus of the huntingtin (HTT) protein." (PMID 32859226, 2020).
Huntington disease (continued). "Huntington’s disease (HD) is an inherited neurodegenerative disorder, caused by an abnormal polyglutamine (polyQ) expansion in the huntingtin protein (Htt)." (PMID 31717806, 2019). "Huntington's disease (HD) is an autosomal dominant neurodegenerative disease caused by the expanded CAG tract resided in the first exon of the Huntingtin (HTT) gene." (PMID 31828084, 2019). "Huntington’s disease is caused by expansion of a polyglutamine tract in the huntingtin protein; mutant huntingtin protein (mHtt) is unstable and accumulates in large intracellular inclusions both in affected individuals and when expressed in eukaryotic cells." (PMID 31527136, 2019). "Huntington disease (HD) is a lethal neurodegenerative disorder caused by expansion of a CAG repeat within the huntingtin (HTT) gene." (PMID 31712634, 2019). "Huntington’s disease is a neurodegenerative disease caused by GAG trinucleotide repeat in the gene encoding the huntingtin protein (HTT)." (PMID 30744021, 2019). "Neurodegenerative diseases including Alzheimer’s Disease (AD), Parkinson’s Disease (PD), and Huntington’s Disease (HD) are caused by the misfolding and aggregation of causal proteins such as amyloid beta, alpha synuclein, and huntingtin, respectively." (PMID 31683805, 2019). "Huntington’s disease (HD) is a progressive neurodegenerative disorder caused by an expanded CAG repeat within the huntingtin (HTT) gene." (PMID 31282030, 2019). "Multiple pathomechanisms triggered by mutant Huntingtin (mHTT) underlie progressive degeneration of dopaminoceptive striatal neurons in Huntington’s disease (HD)." (PMID 31920562, 2019). "Huntington’s disease (HD) is caused by an autosomal dominant gene that produces mutant huntingtin protein that is characterised by abnormally long CAG repeats." (PMID 31720375, 2019). "Rare individuals with inactivating mutations in the Huntington’s disease gene (HTT) exhibit variable abnormalities that imply essential HTT roles during organ development." (PMID 30897080, 2019). "Huntington’s disease is caused by an autosomal dominant mutation in the HTT gene leading to progressive neurodegeneration associated with protein aggregation in the nuclei of neuronal cells." (PMID 31110208, 2019). "The immediate cause of Huntington’s disease is well known: Huntington’s patients have an abnormal, mutant version of a protein called huntingtin." (PMID 30994454, 2019). "For example, a triplet repeat expansion in the Huntingtin gene causes ~ 100% Huntington disease (HD), and while the size of this expansion largely determines age of disease onset, other alleles in the genetic background also modulate this timepoint." (PMID 31203387, 2019). "Oxidative stress is a hallmark of Huntington’s disease and has been shown to occur in cells exposed to mutant huntingtin aggregates." (PMID 31405050, 2019). "Huntington’s disease (HD) is an autosomal dominant neurodegenerative disorder caused by a polyglutamine expansion mutation in the huntingtin protein." (PMID 30502498, 2019). "Huntington’s disease (HD) is a type of hereditary neurodegenerative disorder caused by the aggregation of mutant Huntingtin (mHtt)." (PMID 31391108, 2019). "Huntington disease (HD) is an inherited neurodegenerative disorder caused by a mutation in the huntingtin gene." (PMID 31156395, 2019). "Huntington’s disease (HD) is an inherited neurodegenerative disorder caused by the expansion of the CAG repeat in exon 1 of the huntingtin (HTT) gene, which results in a mutant protein with an extended polyglutamine tract." (PMID 31076648, 2019). "Autophagy is the primary clearance mechanism for several aggregation-prone proteins, such as amyloid-β, α-synuclein and huntingtin, associated with Alzheimer’s, Parkinson’s and Huntington’s disease, respectively; a process termed aggrephagy." (PMID 31555645, 2019).
Huntington disease (continued). "Huntington’s disease (HD) is an autosomal dominant neurodegenerative disease caused by expansion of CAG repeats in the gene huntingtin, htt, present on chromosome 4." (PMID 30941013, 2019). "Huntington’s disease is caused by extension of huntingtin’s N-terminal poly-valley amide which changes protein conformation into β-pleated sheet." (PMID 31341840, 2019). "Huntington's disease (HD) is a neurodegenerative disease caused by mutations in the Huntingtin gene, leading to CAG repeat/poly‐glutamine expansions." (PMID 31617312, 2019). "The variability of disease onset and progression depends on the CAG number, and on genetic modifiers interacting with the Huntingtin mutation [Genetic Modifiers of Huntington’s Disease (GeMHD) Consortium (2015)]." (PMID 31920562, 2019). "Such is the case for Huntington’s disease (HD), a genetic disorder primarily caused by a triplet expansion in the Huntingtin gene (HTT)." (PMID 31798558, 2019). "Huntington's disease is a neurodegenerative disease caused by CAG repeat expansion in the mutant HTT (or IT15) gene, which increases the size of the polyglutamine (polyQ) tract in the N‐terminal of the Huntington (Htt) protein." (PMID 30889315, 2019). "Huntington's disease (HD) is neurodegenerative disorder caused by the expansion of a polyglutamine stretch within the huntingtin protein (Htt)." (PMID 31278192, 2019). "Huntington’s disease is caused by expansion of glutamine repeats near the N terminus of the huntingtin protein (Htt)." (PMID 31527136, 2019). "Pathogenic variants of the huntingtin (HTT) protein and their aggregation have been investigated in great detail in brains of Huntington’s disease patients and HTT-transgenic animals." (PMID 31109380, 2019). "Huntington’s disease (HD) is a neurodegenerative disorder associated with an aberrant expansion of glutamine repeats in the amino terminal domain of the huntingtin protein." (PMID 31726793, 2019). "Huntington’s disease (HD) is characterized by the accumulation of huntingtin (HTT) aggregates and genetic mutations in HTT can drive disease." (PMID 31791377, 2019). "Huntington's disease is a neurodegenerative disorder caused by expansion of polyglutamine repeats in the protein huntingtin, Htt, which causes it to aggregate and cause widespread damage in almost all tissues expressing it." (PMID 31920936, 2019). "Huntington’s disease (HD) is an autosomal dominant neurodegenerative disorder caused by a mutation in the gene that encodes for the protein Huntingtin (Htt)." (PMID 32009905, 2019). "Huntington’s disease (HD) is an inherited neurodegenerative disorder caused by a CAG repeat expansion within exon 1 of the huntingtin (HTT) gene." (PMID 31695145, 2019). "Huntington’s disease (HD) is an autosomal dominant inherited neurodegenerative disorder caused by CAG triplet repeats expansion in exon 1 of the Huntingtin gene (HTT)." (PMID 31595198, 2019). "Huntington’s disease (HD) is a heritable neurological disorder that affects cognitive and motor performance in patients carrying the mutated huntingtin (HTT) gene." (PMID 31139071, 2019). "Huntington’s disease (HD) is an inherited neurodegenerative disease caused by an expanded CAG repeat in the huntingtin (HTT) gene." (PMID 30358836, 2019). "Huntington's disease (HD) is an inherited brain disorder which is caused by a mutated form of the huntingtin gene." (PMID 30766446, 2019). "Huntington's disease (HD) is an inherited neurodegenerative disorder which is caused by a mutation of the huntingtin (HTT) gene." (PMID 30766446, 2019). "Huntington’s disease (HD) is a fatal autosomal dominant genetic disorder caused by an unstable expansion of cytosine–adenine–guanine (CAG) repeats in exon 1 of the huntingtin (HTT) gene." (PMID 31139071, 2019). "Huntington’s disease (HD) is a genetic neurodegenerative disorder caused by the abnormal repetition of CAG nucleotides in the Huntingtin (HTT) gene." (PMID 31614758, 2019).
Huntington disease (continued). "Huntington’s disease (HD) is a neurodegenerative disorder caused by a genetic abnormality in the huntingtin gene that leads to a polyglutamine repeat expansion of the huntingtin protein." (PMID 30961637, 2019). "Huntington’s Disease (HD) is an autosomal dominant disorder caused by expansion of a CAG triplet in the HTT gene that leads to expression of a mutant form of the Huntington protein, HTT." (PMID 31133804, 2019). "Huntington’s disease (HD) is a neurodegenerative disease caused by an expanded CAG repeat in the huntingtin (HTT) gene, causing the protein to misfold and aggregate." (PMID 30941017, 2019). "Huntington’s disease (HD) is a dominantly inherited neurodegenerative condition caused by expansion of a CAG trinucleotide repeat in the huntingtin (HTT) gene." (PMID 30358836, 2019). "Mutations in the huntingtin gene (HTT) are responsible for the onset of Huntington’s disease (HD), and 50% of people with advanced HD develop dementia as well." (PMID 31396511, 2019). "Huntington’s disease (HD) is a fatal inherited autosomal dominant neurodegenerative disorder caused by an expansion in the number of CAG trinucleotide repeats in the huntingtin gene." (PMID 31695068, 2019). "Huntington's disease (HD) is an autosomal dominant neurodegenerative disease due to an expansion of a trinucleotide repeats in IT15 gene encoding for the protein huntingtin." (PMID 30881980, 2019). "Huntington’s Disease (HD) is a neurodegenerative disease caused by a CAG repeat expansion mutation in the exon 1 of the huntingtin (Htt) gene." (PMID 30502498, 2019). "Huntington disease, HD HD is an autosomal-dominant neurodegenerative disorder caused by a polyglutamine tract expansion in the HTT gene, characterised by progressive chorea, dystonia, and cognitive and psychiatric symptoms including dementia." (PMID 31203387, 2019). "In astrocytes, SK1 is cytoprotective and promotes the degradation of an autophagy substrate, mutant huntingtin, the protein that causes Huntington’s disease." (PMID 29743513, 2018). "Huntington’s disease (HD) is a neurodegenerative disorder caused by a tandem repeat mutation encoding an expanded polyglutamine tract in the huntingtin protein, which leads to cognitive, psychiatric and motor dysfunction." (PMID 30618600, 2018). "Huntington’s disease (HD) is a monogenic disorder, caused by mutations in the HTT gene which result in expansion of CAG triplets." (PMID 29435951, 2018). "Huntington's disease (HD) is a monogenic neurodegenerative disorder caused by a CAG‐repeat expansion in the Huntingtin gene." (PMID 29682858, 2018). "Huntington’s disease (HD) is caused by an expanded CAG repeat within the first exon of the Huntingtin (Htt) gene." (PMID 29302618, 2018). "Huntington’s disease (HD) is a dominantly inherited neurodegenerative disease caused by an increase in CAG repeats in the Huntingtin gene (HTT)." (PMID 30451892, 2018). "Huntington’s disease (HD) is a progressive brain disorder caused by the expansion of a CAG repeat in the huntingtin gene." (PMID 29742127, 2018). "Huntington disease (HD) is an inherited neurodegenerative disorder caused by a polyglutamine repeated expansion in the huntingtin (HTT) gene." (PMID 29883458, 2018). "The model simulates human Huntington’s disease through CAG repeats in the huntingtin allele, with 35 or more repeats resulting in polyglutamine (polyQ) mediated aggregation, protein misfolding, and cellular toxicity." (PMID 30374138, 2018). "Huntington’s disease is caused by the expansion of a CAG repeat in the open-reading frame of the huntingtin gene (HTT), which translates into an expanded glutamine stretch in the aberrant, mutant protein (mHTT)." (PMID 30179155, 2018). "Huntington’s disease (HD) is a hereditary neurodegenerative disease that is caused by polyglutamine expansion within the huntingtin (HTT) gene." (PMID 30455632, 2018).